INS (insulin)
Diseases named in the same sentence as INS in open-access papers (continued):
Sharing a sentence is not in itself a finding about the gene and the disease.
type 1 diabetes (continued). "In Type 1 diabetes a reduction in glycaemic variability with restoration of even small amounts of residual insulin secretion has been demonstrated after islet transplantation." (PMID 22681724, 2012). "An educational program involving a low-carbohydrate diet and correspondingly reduced insulin doses for informed individuals with type 1 diabetes gives acceptable adherence after 4 years." (PMID 22650646, 2012). "Since the islets fail to produce insulin altogether, the only treatment options for type I diabetes are exogenous delivery of insulin and pancreas or islet transplantation." (PMID 22675353, 2012). "Insulin amyloid formation is characteristic of localized amyloidosis that is observed in patients with insulin dependent diabetes who frequently receive insulin." (PMID 22848469, 2012). "Type I diabetes (T1D) is an autoimmune disease characterized by T cell-mediated destruction of insulin-producing beta cells." (PMID 23272217, 2012). "Type 1 diabetes (T1D) is characterized by the autoimmune destruction of the insulin-secreting β cells residing in the pancreatic islets of Langerhan’s." (PMID 23251685, 2012). "AH patients with type 1 diabetes and many with type 2 will be treated with subcutaneously injected insulin." (PMID 22613296, 2012). "Intensive insulin regimens with prandial rapid or short acting insulin are clearly appropriate in Type 1 diabetes outside the honeymoon period where there is absolute insulin deficiency." (PMID 22681724, 2012). "Type 1 diabetes mellitus (T1D) is an early-onset autoimmune disease in which immune response is directed against the insulin-producing beta cells of the pancreas, resulting in insulin-dependence." (PMID 22745776, 2012). "Patients in the lowest tertile of endogenous insulin secretion were likely to be diagnosed younger and have lower BMI, consistent with a greater proportion having type 1 diabetes, but had similar HbA1c compared with the other tertiles." (PMID 22681724, 2012). "Transplantation of human islets is an attractive alternative to daily insulin injections for patients with type 1 diabetes." (PMID 22666480, 2012). "As islet autoantibodies predict type 1 diabetes, it is imperative to clarify the mechanisms of insulin autoimmunity." (PMID 22567309, 2012). "Early detection provides the opportunity for the disease to be managed using life-style changes; however, disease progression and eventual reduction in β-cell mass require insulin supplementation, similar to the pathology of type 1 diabetes." (PMID 22851965, 2012). "As an antidiabetes therapy, insulin has been the best studied and more efficient pharmacological compound mainly used in the treatment of type 1 diabetes." (PMID 22500228, 2012). "Hepatic glycogenosis has been reported to occur at first presentation of type 1 diabetes after receiving supraphysiological doses of insulin." (PMID 23039762, 2012). "In patients with type 1 diabetes secretion of both counter-regulatory hormones of insulin and glucagon is severely interrupted." (PMID 23497433, 2012). "Type 1 diabetes mellitus is characterized by an impaired ability to produce insulin due to the progressive and selective destruction of beta cells in the pancreatic islets of Langerhans by the immune system." (PMID 22973412, 2012). "In support of this, infusion of adenosine increases insulin sensitivity in patients with type 1 diabetes mellitus (T1DM)." (PMID 22844517, 2012). "These measurements suggest that endogenous insulin production increases following onset of type 1 diabetes and then slowly declines in the subsequent years." (PMID 22073210, 2011). "Type 1 diabetes (T1D) is an autoimmune disease that results in the destruction of pancreatic insulin-producing beta cells." (PMID 21765850, 2011). "In these patients, recognition of metabolic, immunological, and genetic markers of type 1 diabetes will allow patients to remain on insulin therapy because diet and oral pharmacological therapy are likely to fail." (PMID 21461382, 2011).
type 1 diabetes (continued). "Most of these studies are conducted in healthy volunteers (low doses) to ascertain safety and patients with type 1 diabetes (treatment doses) to describe more fully, insulin metabolism and glucose lowering effect." (PMID 21410860, 2011). "Case 1 is a 91-year-old Japanese woman who had been diagnosed with acute onset of type 1 diabetes two years earlier and had been using various doses and types of insulin since that diagnosis." (PMID 21443773, 2011). "Diabetes type 1 is a chronic autoimmune disease that is characterized by the destruction of insulin-producing cells." (PMID 21584225, 2011). "Increased right ventricular weight compared to the left ventricle plus the septum weight has been described in streptozotocin-induced type 1 diabetes and in insulin resistant ApoE knockout mice." (PMID 21513515, 2011). "T1D, also called insulin-dependent diabetes, is treated by administration of insulin through injection." (PMID 22654727, 2011). "Limited data have been reported on MCP-1 in type 1 diabetes (T1D), an autoimmune disease characterized by lymphocyte infiltration into the pancreatic islets and destruction of the insulin-producing islet β-cells in children and young adults." (PMID 21532752, 2011). "Type 1 diabetes is characterized by the autoimmune destruction of β cells, resulting in life-long dependency on insulin injection that often results in complications of hypo- or hyperglycemia." (PMID 21687731, 2011). "The majority of insulin pharmacology studies are conducted in healthy volunteers and patients with type 1 diabetes." (PMID 21410860, 2011). "For persons with type 1 diabetes, intensive insulin therapy (e.g., injections, pump therapy) is needed, along with self-monitoring of blood glucose (SMBG) often multiple times per day." (PMID 21917132, 2011). "Type 1 diabetes (T1D) is a chronic autoimmune disorder characterized by dysregulated blood-glucose (BG) levels due to an inability of the pancreas to produce insulin, the hormone that promotes uptake of glucose by cells." (PMID 21590789, 2011). "Results of pharmacodynamic studies of patients with type 1 diabetes are easier to interpret as almost all glucose lowering is attributed to the study insulin." (PMID 21410860, 2011). "Our objective was to determine the cost-effectiveness of Continuous Glucose Monitoring (CGM) technology with intensive insulin therapy compared to self-monitoring of blood glucose (SMBG) in adults with type 1 diabetes in the United States." (PMID 21917132, 2011). "Insulin-sensitizing drugs from the thiozalinedione class have revolutionized the treatment of insulin-dependent diabetes yet have been beset by rare but serious side effects." (PMID 22162991, 2011). "He leads research team developing and testing closed-loop insulin delivery systems in type 1 diabetes, and he also works on developing approaches for glycemic control in the critically ill." (PMID 22071283, 2011). "Diabetes type 1 is a chronic autoimmune disease in which insulin-producing cells are gradually destroyed by autoreactive T cells." (PMID 21584225, 2011). "The feasibility and efficacy of MPC-based closed-loop insulin delivery was also recently demonstrated in women with type 1 diabetes throughout different stages of pregnancy." (PMID 22071283, 2011). "The objective of this analysis is to assess the cost-effectiveness of CGM with intensive insulin therapy relative to standard care (i.e., SMBG with intensive insulin therapy) in a general U.S. population of individuals with type 1 diabetes." (PMID 21917132, 2011). "Current therapies for type 1 diabetes focus primarily on administration of exogenous insulin to help restore glucose homeostasis." (PMID 21716654, 2011). "Children with type 1 diabetes (DM1) require multiple daily injections of insulin to maintain good glycemic control." (PMID 22067102, 2011).
type 1 diabetes (continued). "Many patients with Type 1 diabetes who use large doses of insulin to cover for their excessive intake of carbohydrates are also insulin resistant." (PMID 21668983, 2011). "Approximately 95% of patients with Type 1 diabetes develop some degree of retinopathy within 25 years of diagnosis despite normalization of blood glucose by insulin therapy." (PMID 21575160, 2011). "Closed-loop insulin delivery, also referred to as the artificial pancreas, is an emerging therapeutic approach for people with type 1 diabetes." (PMID 22071283, 2011). "Sixty anti-GAD positive patients with a five year non-insulin dependent diabetes profile were randomized to either early insulin or sulfonylureas, tested annually for C-peptide secretion under an oral glucose tolerance test and followed up for 57 months." (PMID 21785617, 2011). "Susceptibility genes for insulin dependent diabetes have been mapped to the chromosomal regions: HLA DRQ, INS VNTR and CTLA-4 (cytotoxic lymphocyte antigen-4)." (PMID 20350307, 2010). "All patients with type 1 diabetes used insulin, whereas 77 persons (92%) of patients with type 2 diabetics used insulin medication." (PMID 20123602, 2010). "This sensor has been shown to be useful for outpatient care by enabling individuals with type-1 diabetes to manually adjust their subcutaneous insulin doses according to the glucose levels displayed by the device." (PMID 20642855, 2010). "NOD mice spontaneously develop insulitis and type 1 diabetes (T1D), an autoimmune disease characterized by T cell-mediated destruction of the insulin-producing beta cells of the pancreas." (PMID 21188239, 2010). "Anti-GM1 antibodies have previously been found in the sera of patients with polyneuropathy and either insulin-dependent or non-insulin-dependent diabetes." (PMID 21176139, 2010). "The introduction of human insulin in the 1990s led to an increase in the number of sudden nocturnal deaths of young people with type I diabetes." (PMID 21234404, 2010). "Type 1 diabetes (T1D) is an autoimmune disease, often diagnosed early in life, characterized by the destruction of the insulin-secreting β cells in the pancreas." (PMID 20634976, 2010). "Modern treatment of type 1 diabetes includes individualized education, intense multiple-dose treatment regimens, active self-control, and new insulin and insulin delivery technologies." (PMID 20511179, 2010). "Allantoin, a product of nonenzymatic urate oxidation, was significantly elevated with insulin deprivation, indicative of increased oxidative stress when insulin is withdrawn from patients with type 1 diabetes." (PMID 20479934, 2010). "DAFNE (Dose Adjustment for Normal Eating) is a 5-day out-patient course for adults with Type 1 diabetes, teaching the skills of carbohydrate counting and insulin dose adjustment." (PMID 20633252, 2010). "A quarter of a century ago, the introduction of capillary blood glucose monitors allowed Type-1 diabetics to intermittently measure their glycemia and adjust their subcutaneous insulin dosage 3 to 4 times a day using empirical algorithms." (PMID 20642855, 2010). "The rapid IOP fall in patients with type 1 diabetes in response to intravenous insulin is a novel finding." (PMID 20573241, 2010). "Compared to healthy controls, patients with type 1 diabetes are more insulin resistant and are exposed to higher insulin concentrations." (PMID 20573241, 2010). "A recent glucose-clamp study compared duration of action of insulin glargine and insulin detemir after single and repetitive doses (administration over 7 days) in subjects with type 1 diabetes." (PMID 20618882, 2010). "The whole body glucose infusion rate during the last 30 minutes of the clamp, an indication of insulin sensitivity, was lower in patients with type 1 diabetes, compared to controls (7.6 ± 3.7, versus 11.7 ± 2.9 mg/kg/min, respectively, p = 0.01)." (PMID 20573241, 2010).
type 1 diabetes (continued). "Both type 1 diabetes (T1D) and type 2 diabetes (T2D) ultimately result from an inadequate number of functional insulin-producing beta cells in the islets of Langerhans." (PMID 21318185, 2010). "Even with rigorous glucose control, patients with type 1 diabetes often experience insulin and glucose fluctuations that apparently affect IOP." (PMID 20573241, 2010). "Decreased blood glucose levels and also reduction of glucose excursion after meals were observed in recent−onset type 1 diabetic patients treated with intravenous or subcutaneous GLP−1 with concurrent administration of multiple dose insulin therapy." (PMID 21274399, 2009). "The duration of the type 1 diabetes varied between 4 and 31 years (mean 15 years); most women administered insulin by pen, and some by pump." (PMID 19575789, 2009). "Type 1 diabetes (T1D) is a T-cell mediated autoimmune disease targeting the insulin-producing pancreatic β cells." (PMID 19654878, 2009). "Type 1 diabetes (T1D) is an autoimmune disease that results in destruction of insulin-producing beta cells of the pancreas." (PMID 19798418, 2009). "Type 1 diabetes (T1D) results from the T-cell-mediated autoimmune destruction of the insulin-producing pancreatic islet β cells." (PMID 19654878, 2009). "Type 1 diabetes is a common and multifactorial disease characterized by autoimmune-mediated destruction of the insulin-producing beta cells of the pancreas." (PMID 19888425, 2009). "Type 1 diabetes occurs when the body's immune system prevents the production of insulin, the hormone that controls blood glucose." (PMID 19997624, 2009). "For these women with type 1 diabetes, the overall goal of giving birth to a healthy baby required frequent blood glucose checks and insulin adjustment." (PMID 19575789, 2009). "Type 1 diabetes (T1D) is a multifactorial, autoimmune disorder where the insulin producing pancreatic beta cells are destroyed by one's own immune system." (PMID 19956544, 2009). "Type 1 diabetes is a multifactorial disease with an early age of onset, in which the insulin producing β cell of the pancreas are destroyed because of autoimmunity." (PMID 20142874, 2009). "Auto-antibodies to antigens such as glutamate decarboxylase (GAD) and insulin have been reported in both NOD mice and type 1 diabetic patients although the direct pathogenic role of auto-antibodies is still controversial." (PMID 18773086, 2008). "An 80-year old female with Type 1 diabetes, who takes insulin (Humlin® 70/30) twice daily, documented her blood sugar levels before breakfast and before dinner for one week." (PMID 18568931, 2008). "In type 1 diabetes in which endogenous insulin secretion is completely depleted, basal-bolus insulin therapy with an ultra rapid-acting insulin analogue represents an optimal therapeutic choice as it closely mimics physiologic insulin secretion." (PMID 18507868, 2008). "While insulin replacement remains the cornerstone treatment for type 1 diabetes, the transplantation of pancreatic islets of Langerhans provides a cure for this disorder." (PMID 18298656, 2008). "By adolescence, children with type 1 diabetes typically receive three or more insulin injections per day, placing a substantial burden on their parents." (PMID 18205937, 2008). "Its primary mode of action is to induce insulin secretion by pancreatic β-cells and as a result, it is ineffective, when administered alone, in the treatment of insulin dependent diabetes (Type I diabetes)." (PMID 20157366, 2008). "Within the section Protein pathway involvement in disease, type 1 diabetes arises from an immunological destruction of the insulin producing β-cells." (PMID 19007436, 2008). "Despite intensive insulin treatment, many patients with type-1 diabetes (T1DM) have longstanding inadequate glycaemic control." (PMID 18852875, 2008).
type 1 diabetes (continued). "The use of insulin for the treatment of GDM, which reflects the severity of the disease, was shown to be an independent risk factor for the occurrence of postpartum Type 1 diabetes." (PMID 18588707, 2008). "Type 1 diabetes is presumed to originate from an autoimmune process and is usually controlled by the administration of insulin." (PMID 19902046, 2008). "Guidelines for optimizing type 1 diabetes in young people advocate intensive insulin therapy coupled with personal support from the health care team." (PMID 18653444, 2008). "In type 1 diabetes, good glycemic control usually requires at least two or more often three or more daily insulin injections." (PMID 20046733, 2008). "This study was carried out to determine the costs of SH in a population of patients with type 1 diabetes in the Spanish healthcare system and the incremental cost-effectiveness of insulin lispro over regular insulin in preventing SH episodes." (PMID 18489577, 2008). "Islet cell transplantation can cure type 1 diabetes (T1D), but only a minority of recipients remains insulin–independent in the following years." (PMID 18560516, 2008). "Some researchers have begun to set foot in the field of MSCs-based insulin gene therapy for type 1 diabetes." (PMID 18298656, 2008). "Insulin-producing cells generated either by transdifferentiation of MSCs or by delivery of insulin gene into MSCs are able to act as replacement β-cells for the transplantation therapy of type 1 diabetes." (PMID 18298656, 2008). "Effect of metformin versus placebo on follow-up (intermediate and study visit) levels of HbA1c and insulin doses in 72 patients with type-1 diabetes during a one year period." (PMID 18852875, 2008). "Typically, the closed-loop system for type 1 diabetes therapy utilizes the glucose sensor and schematically consistsof three phases: blood glucose measurements, insulin demand calculation, andinsulin injection." (PMID 18437199, 2008). "Individuals with Type 1 diabetes on ‘intensive’ insulin therapy are also typically subject to these glycaemic excursions, with 72-h continuous monitoring recording postmeal elevations above 7.8 mmol/l (140 mg/dl) in 77% of this patient population." (PMID 19046192, 2008). "The combined injection of insulin andC-peptide required a greater amount and longer duration of glucose than insulinalone in patients with diabetes type 1." (PMID 18389076, 2008). "As far as type 1 diabetes is concerned, insulin gene therapy using MSCs is an alternative treatment." (PMID 18298656, 2008). "Type 1 diabetes, which accounts for around 10% of cases in most populations, is due to an autoimmune-mediated destruction of the insulin-producing β-cells in the pancreatic islets of Langerhans." (PMID 19007436, 2008). "Type I diabetes (TID) is an autoimmune disease resulting from destruction of the insulin-producing β-cells by autoreactive T cells." (PMID 18793419, 2008). "In short, in type 1 diabetes, from the malfunction of thepancreas resulting from the destruction of the β cells of the Islets ofLangerhans, a supply of endogenous insulin completely stops." (PMID 18566688, 2008). "Search terms were a combination of the gene symbol with any of these seven key words: Type 1 diabetes, diabetes mellitus 1, beta cell, islets of Langerhans, insulin, autoimmune, or autoimmunity." (PMID 19471607, 2008). "An early diagnosis of Type 1 diabetes is shown to preserve endogenous insulin secretion and to decrease the frequency of micro-vascular complications." (PMID 18588707, 2008). "Self-monitoring blood glucose (SMBG) improves glycaemic control in patients with type 1 diabetes and possibly also in insulin-treated type 2 diabetes (T2D), especially when treated with multiple insulin injections per day." (PMID 18769484, 2008).